MYC (MYC proto-oncogene, bHLH transcription factor)
Diseases named in the same sentence as MYC in open-access papers (continued):
Sharing a sentence is not in itself a finding about the gene and the disease.
tumor (continued). "Tameire's study indicated that ATF4 plays an important role in MYC driven tumor progression." (PMID 33628101, 2021). "One clinical implication of these findings is that androgen deprivation therapies for PCa result in a compensatory increase in MYC, which may be important for initial tumor cell survival." (PMID 34911936, 2021). "MAX behaves as a classical tumour suppressor gene that encodes for the MAX protein, which interacts with the MYC proto-oncogene and the MAX dimerization protein 1 (MXD1) family of proteins; this MYC/MAX/MXD1 network regulates cell proliferation, differentiation and apoptosis." (PMID 33815275, 2021). "Their recruitment is essential for MYC-dependent transformation, but dispensable for the activation of physiological MYC targets, suggesting that MYC induced epigenetic remodeling is a limiting step in tumor development." (PMID 34201047, 2021). "Interestingly, both reports agreed that Group 3 MB tumours with MYC amplification or overexpression have a dismal outcome and the poorest prognosis, highlighting that it is of a paramount importance to tailor MB treatments to its biology." (PMID 33686114, 2021). "From these data, it might be concluded that activation of stromal c-MYC is critical for re-programming of stromal cells, and that inhibition of LO internalization might impair the tumor-supporting properties of fibroblasts by preventing c-MYC activation." (PMID 34772427, 2021). "We speculated that HOXB9 might block the Wnt signaling pathway and inhibit tumor growth through MYC and CTNNB1." (PMID 34306077, 2021). "In order to clarify the relationship between normal and tumor cells, we grouped other genes according to how much MYC was expressed and obtained 213 differentially expressed genes—among which, 141 (66.20%) genes were upregulated, and 72 (33.80%) genes were downregulated (log2|FC| = 2, p < 0.05)." (PMID 33540574, 2021). "In addition to its multiple implications in controlling cancer cell biology, MYC`s important role in remodeling the tumor microenvironment (TME) is emerging." (PMID 34637026, 2021). "Hence, major scientific efforts have focused on gaining a better understanding of MYC-mediated apoptosis in an attempt to identify key targets inactivated in tumor cells." (PMID 33801599, 2021). "Paradoxically, MYC expression in late passage fibroblasts is associated with tumours that grow less aggressively and with decreased ability to metastasise, as compared to for example RAS-expressing tumours, with cell loss by apoptosis commonly observed." (PMID 33799592, 2021). "Furthermore, the results showed that FOXC1 can promote growth of GC by modulating the tumor cell cycle, as mediated by c-MYC and cyclin D1, further supporting the role of FOXC1 in GC progression." (PMID 33987183, 2021). "In fact, above induction of the pro-survival and proliferation gene, MYC controls the expression of different immune checkpoint proteins on the tumor cell surface, such as the innate immune regulator, CD47 (cluster of differentiation 47), and NK-activating ligands, such as MICA/B and PVR." (PMID 34503175, 2021). "The miR-26a targeting c-MYC mRNA induced tumor regression in HCC." (PMID 33958005, 2021). "The function of c-MYC is also necessary for the angiogenic switch required for tumor progression." (PMID 33923319, 2021). "MYC mRNA and protein overexpression in PCa tumour foci corresponds with disease severity." (PMID 34771740, 2021).
tumor (continued). "A corollary of this hypothesis is that the lack of MYC-induced transcriptional stress would relieve the need for genetic adaptation during tumor development, thus leaving MYC-dependent tumors liable to therapeutic strategies that evoke TDRS." (PMID 34201047, 2021). "Since the T-cell-stimulatory capacity of λ-MYC tumor-derived TIDCs was compromised, we asked the question whether the tumor-dependent functional impairment of DCs can be attenuated by ICB." (PMID 33141285, 2021). "MiR-34 is another miRNA family that controls the expression of the MYC gene in various tumor types." (PMID 34440124, 2021). "The authors then proposed that CCAT1 may serve as a clinical biomarker to predict which cancers utilize BET activity to drive MYC transcription and tumor growth, and to identify patients who are likely to benefit from BET inhibitors." (PMID 34065438, 2021). "Additionally, low tumor cellularity also likely contributed to the underestimation of copy gains of the MYC locus in these cases." (PMID 34445161, 2021). "Moreover, many basal-like tumours exhibit hyperactivated MYC proto-oncogene (MYC) signalling, which leads to the upregulation of genes involved in glucose metabolism." (PMID 34572926, 2021). "However, MYC also maintains the proliferation of non-tumor cells and lacks effective binding pockets for small-molecule drugs, making its direct pharmacological inhibition challenging." (PMID 34207158, 2021). "We and others have shown that CIP2A regulates MYC, is essential for tumor growth, tissue regeneration, and thus may open a therapeutic window for targeting tumors." (PMID 33078202, 2021). "Notably, PLX and PD synergistically attenuate MYC transcription to induce p27 for the tumor suppression." (PMID 34761120, 2021). "MYC is very crucial for angiogenesis which is a key factor for the aggressive behavior of a tumor." (PMID 33958005, 2021). "Tumour latency in this mouse model is typically six-months prior to the onset of disease, with high levels of apoptosis detected in the B-lymphocyte compartment consistent with the induction of apoptosis due to high MYC levels." (PMID 33799592, 2021). "Based on the experimental data, it was suggested that inhibiting c-MYC expression may stop tumour growth." (PMID 35053185, 2021). "The response to OTX105 differs in tumor types encompassing mechanisms that include suppression of cell proliferation and viability, downregulation of MYC/MYCN proteins and MYC-regulated transcriptional programs, loss of stemness features and chromatin remodeling." (PMID 33668642, 2021). "Many of the tumor oncogenic effects were fulfilled through the MYC and/or SOX2." (PMID 34898574, 2021). "Importantly, we demonstrated that miR-22 exerted its tumor growth inhibitory activity mostly in MYC-proficient cells, further providing evidence of a miR22/MYC axis as a viable and attractive therapeutic target in MM." (PMID 34503175, 2021). "Clinically, these findings indicate that increased MYC in response to androgen deprivation contributes to the development of CRPC, while decreased MYC may contribute to tumor regression in response to supraphysiological androgen therapy in men with CRPC." (PMID 34911936, 2021). "In addition, MYC inhibition hampered tumor growth, enhanced tumor immune cell infiltration, upregulated PD-L1 expression, and sensitized anti-PD1 immune response." (PMID 34088360, 2021). "Interestingly, in humans, high MYC tumor cells also correlate with the induction of cell death in surrounding stromal cells." (PMID 33861719, 2021).
tumor (continued). "Here, we show a small peptide derived from the Kaposi’s sarcoma-associated herpesvirus transactivator (K-Rta) sequence, which attenuates cellular MYC expression, reduces cell proliferation, and selectively kills cancer cell lines in both tissue culture and a xenograft tumor mouse model." (PMID 34857874, 2021). "Several studies underline the importance of oncogenic Ras-mediated metabolic shifts in tumor progression, which could influence and enhance the MYC-regulated cellular events via activation of the Raf/Mek/Erk pathways." (PMID 35029792, 2021). "MGA, a transcription factor which interacts with c‐MYC, is a putative tumor suppressor gene." (PMID 33811746, 2021). "In mouse models, MYC withdrawal has led to tumor regression, indicating that MYC may be a valuable target in SCLC." (PMID 34531756, 2021). "By partitioning cells into groups having consistent patterns of CNVs, we observed that Vκ*MYC tumours are comprised of 4–8 malignant cell subpopulations with distinct CNV profiles, underscoring the power of scRNA-seq to delineate malignant subpopulations not detected by bulk approaches." (PMID 34732728, 2021). "MGA is a tumor suppressor gene (TSG) that binds to MAX and inhibits MYC-dependent tumor growth." (PMID 34733843, 2021). "Similarly, EZH2 and DOT1L are other histone methyltransferases whose inhibition leads to MYC downregulation, resulting in tumor growth suppression through slightly different mechanisms." (PMID 35582389, 2021). "Genes already strongly bound to MYC in normal cells, associated for example with ribosome function, were not modulated by increased tumor-specific MYC levels." (PMID 33801599, 2021). "MYC is a transcription factor known to be involved in tumor progression." (PMID 34564151, 2021). "Responding tumours had evidence of deregulated MYC expression." (PMID 33311588, 2021). "We hypothesize that combined inhibition of transcription (by BET-protein inhibition) and translation (by mTOR inhibition) will synergistically blockade global protein synthesis and proliferation in MYC-driven NB tumor cells." (PMID 34565342, 2021). "To evaluate this hypothesis, we performed a tumor induction study in MYC-transgenic mice infected as neonates with the Moloney-derived murine leukemia virus, MOL4070LTR." (PMID 34876184, 2021). "We stratified the patients for MYC amplification and stage of the tumour." (PMID 34423893, 2021). "Moreover, when tumors that expressed active phosphorylated mutants of MYC at S62 or Th58 were studied, there was an increase of tumor resistance to statin treatment which supported the role of serine/threonine phosphatase PP2A as a negative regulator of MYC." (PMID 33718197, 2021). "Inhibitors that downregulate MYCN/MYC proteins can suppress N.B. tumor growth." (PMID 34943600, 2021). "More importantly, MYC also regulates the immune cell function in the tumor microenvironment." (PMID 34122516, 2021). "The cell cycle (Cycling) program was characterized by high expression of genes involved in cell proliferation (e.g., CENPW, CKS1B, and BIRC5) and presented activation of the E2F targets, G2M checkpoint and MYC targets pathways, suggesting tumor cell proliferation." (PMID 34489433, 2021). "In addition to the previously identified germline BRCA alteration in this case, CDK4 and MYC copy number alterations were identified by NGS of matched tumor-normal tissue, informing subsequent treatment decisions." (PMID 33619265, 2021). "Furthermore, analysis of the tumour-stroma interface in a number of human tumour samples found a strong correlation between elevated MYC levels in the tumour and activated caspase-3 expression in the adjacent stroma." (PMID 31102668, 2020). "Indeed, the tumor cells have acquired specific mechanisms for mitigating the apoptotic effects that MYC imposes in their normal counterparts." (PMID 32549409, 2020). "Together, MYC controls the expression of genes involved in almost all aspects of tumor hallmarks." (PMID 33251216, 2020).
tumor (continued). "Indeed, PHLPP2 can dephosphorylate MYC at residue Thr58 to prevent MYC degradation and promote tumor progression." (PMID 32630372, 2020). "However, in most studies, MNT acted as a tumor suppressor and was a functional antagonist of MYC by repressing its activities related to cell cycle, proliferation, and apoptosis." (PMID 33261009, 2020). "It is additionally reported that TAM infiltration in neuroblastomas is associated with the induction of MYC expression via IL-6/STAT3 pathway, showing that there are putative feedback loop mechanisms in regulating the expression of MYC in the tumor microenvironment." (PMID 33081056, 2020). "However, the biological significance of MYC paralogs in SCLC development, and the underlying mechanisms of the anti-tumor effects of BET inhibition (BETi) in SCLC, requires further characterization." (PMID 33134168, 2020). "Targeting FASN may be helpful for the treatment of human HCC, at least in the tumor subset displaying c-MYC amplification or activation." (PMID 33187130, 2020). "Menin promotes glycolysis through MYC for tumor progression." (PMID 32971831, 2020). "From our analysis of acyl carnitines in TRAMPC1 and MyC-CaP cells, it is reasonable to speculate that fatty acid-carnitine derivatives produced by the tumor cells could be supporting the fat oxidation phenotype of the tolerogenic TME, supporting cancer growth." (PMID 33352903, 2020). "Moreover, pilling studies show that MYC is heavily involved in educating tumor-infiltrating cells and making them participate in tumor progression." (PMID 33081056, 2020). "c-MYC appears to be a key target of metformin, which could explain several of the anti-tumor effects observed." (PMID 33081077, 2020). "Additionally, MYC was shown to enable the tumour cells to overcome a latent cell cycle arrest in G2/M phase by directly binding AURKA." (PMID 33078469, 2020). "Also, epigenetic treatment of combining DNA-demethylating agents with histone deacetylase inhibitors decreased MYC signaling, exerting robust anti-tumor effect in NSCLC." (PMID 32723974, 2020). "In this cross-sectional descriptive study, we evaluated the expression of E2F1, MYC, and miR-17-5p by quantitative real time PCR analysis in 60 PitNETs: 29 gonadotroph (GT), 15 functioning somatotroph (ST), and 16 corticotroph (CT) tumours, of which 8 were silent (sCT)." (PMID 32316225, 2020). "MYC expression is deregulated and increased through different mechanisms in tumor cells." (PMID 32549409, 2020). "Similarly, the expression of high levels of c-MYC in tumor cells leads to an increase in total levels of transcripts in each cell." (PMID 33628735, 2020). "Down-regulation of MYC was also observed in LUCAT1-KO tumor tissue by IHC staining than NC group." (PMID 33097685, 2020). "Interestingly, MYC is expressed in 40% of FGFR1-amplified tumors and tumor cells co-expressing MYC and FGFR1 are more sensitive to FGFR inhibition." (PMID 33317057, 2020). "HSP90AA1 can exert its tumor-promoting effect by stabilizing c-MYC protein in several cancer types." (PMID 32576198, 2020). "CCAT2 is overexpressed in various types of cancers and may contribute to tumor growth, metastasis, and chromosomal instability by increasing MYC expression." (PMID 32523949, 2020). "NR4A nuclear receptors are tumor suppressors of AML that function in part through transcriptional repression of the MYC-driven oncogenic program via mechanisms that remain unclear." (PMID 32071334, 2020). "It is already established that MYC is essential in the instruction of tumor microenvironment." (PMID 33081056, 2020). "Previous studies showed that treatment with JQ1 at 50 mg/kg could effectively downregulate MYC expression in multiple xenograft tumor models." (PMID 32591507, 2020).
tumor (continued). "Indeed, the stem cell factors Nanog and Sox2 facilitate MYC regulation of HIF2α, playing a critical role in stem cell renewal and tumor stemness." (PMID 33251216, 2020). "The combination synergistically repressed oncogenic MYC and activated the Cdkn2a tumor suppressor." (PMID 32923678, 2020). "MYC plays a central role in the metabolic plasticity of tumor cells." (PMID 31968688, 2020). "Notch2 could promote tumor proliferation through regulating the levels of MYC (r = 0.8, P < 0.001) and MKI67 (r = 0.89, P < 0.001)." (PMID 33425722, 2020). "Thus, recent efforts focus on investigating methods to indirectly target MYC to achieve anti-tumor effects." (PMID 33628735, 2020). "Our tumor organoids showed significant MYC signaling enrichment in GSEA." (PMID 32962010, 2020). "On the other hand, more studies are needed to establish a relationship between MYC expression and PitNET invasiveness, because its behaviour could depend on the tumour subtype." (PMID 32316225, 2020). "Meanwhile, ZNF300 might activate CDK1 through inhibition of WEE1 and MYT1 and modulation of the MYC/AURKA/BORA/PLK1 axis to promote the tumour cells to overcome G2 arrest and enter the M phase to avoid the apoptosis induced by chemotherapeutic drugs." (PMID 33078469, 2020). "Impaired NOTCH1 activity may result in the activation of specific oncogenes (c-MYC, NFkB, or mTOR) or inhibition of tumor suppressor expression (FBXW7, PTEN, CDKN1B)." (PMID 32766158, 2020). "We considered that Twist1 could be influencing MYC expression levels, but MYC levels were similar between the two tumor models, while Twist1 was only overexpressed in the MYC/Twist1-HCC." (PMID 31933479, 2020). "In CRC, a MAX/MYC heterodimer induced by elevated HIF-2α mediates transcriptional repression of hypoxia-related miR-15-16, leading to tumor angiogenesis and hematogenous metastasis by further loss of post-transcriptional restriction towards fibroblast growth factor-2." (PMID 32102656, 2020). "It has been recently proven that MYC favors an immunosuppressive tumor microenvironment." (PMID 33081056, 2020). "However, data presented above clearly demonstrates that MYC can also directly control cellular invasion and migration, hence, metastasis, by regulating the expression of specific gene patterns and recruiting tumor-infiltrating cells." (PMID 33081056, 2020). "Recent preclinical studies indicate that MYC not only contributes to tumorigenesis by its effects on cell proliferation and differentiation, but also plays an important role in promoting escape from anti-tumor immune responses." (PMID 33092116, 2020). "MYC amplification, a hallmark high-risk feature almost exclusive to Group 3, was absent in our adult cohort, including in Group 3 tumours." (PMID 33172502, 2020). "Silencing of MYC in multiple tumor models by using small interfering (si)RNAs leads to tumor regression, suggesting that MYC may be exploited for therapy." (PMID 33318047, 2020).